CD226 (CD226 molecule)
Diseases named in the same sentence as CD226 in open-access papers (continued):
Sharing a sentence is not in itself a finding about the gene and the disease.
autoimmune disease (continued). "Accumulating evidence shows that CD226 is closely related to the occurrence of autoimmune diseases, infectious diseases, and tumors." (PMID 32850777, 2020). "TIGIT and CD226 costimulatory axis plays an important role in the immunoregulatory function of Foxp3 + Tregs and is related to several autoimmune diseases." (PMID 32850777, 2020). "Considering that Treg and dendritic cells are involved in the pathogenesis of autoimmune disease, exploring the balance of the CD226/TIGIT immune checkpoint in these cells is also needed for a deeper understanding of PBC." (PMID 32793241, 2020). "The results of our previous studies demonstrated that mice treated with an anti-CD226 pAb in vivo have markedly decreased EAE susceptibility, in agreement with recent data showing that CD226 is involved in the pathogenesis of autoimmune diseases." (PMID 32983109, 2020). "These novel findings confirmed that CD226 played a pivotal role in mediating autoimmune diseases such as EAE." (PMID 26942885, 2016). "So far, the contribution of CD226/DNAM-1 to the phenotype of several autoimmune diseases has been demonstrated in vivo in some murine models." (PMID 25685070, 2015). "Recently, a non-synonymous single nucleotide polymorphism (SNP) Gly307Ser (rs763361) in the CD226 gene, which encodes the DNAX accessory molecule 1 (DNAM-1), has been associated with multiple autoimmune diseases including RA." (PMID 25685070, 2015). "The possibility of CD226 affecting the treatment of autoimmune diseases has also been suggested." (PMID 38612837, 2024). "These include Il-7 and its receptor Il7R, CD226, CAPSL, and CLEC16A, which appear to be attractive candidates for further studies to explore the pathogenic mechanisms and potential therapeutic options for autoimmune diseases." (PMID 38612837, 2024). "Blocking CD226 signals might decrease the generation of Tfh cells and their precursors in patients with autoimmune diseases." (PMID 35273617, 2022). "On the basis of the results of genome-wide association studies and functional analyses of mCD226 on T cells or NK cells, CD226 is thought to play an important role in the pathogenesis of autoimmune diseases such as SLE8–11,15, RA11,24–27, and systemic sclerosis." (PMID 34373559, 2021). "Additionally, CD226 has also been demonstrated to be involved in the pathogenesis of autoimmune diseases by promoting self-reactive CD4+ T cell activation and triggering naïve CD4+ T cell differentiation and proliferation." (PMID 32983109, 2020). "Although the role of CD226 in autoimmune diseases has been well-documented, the molecular mechanisms associated with CD226 activity in these diseases are not clear." (PMID 32983109, 2020). "More importantly, experiments with CD226 knockout mice further proved the protective effects of CD226 ligation, offering solid evidence of the positive effects of CD226 on the pathogenesis of autoimmune diseases manifested here by EAE." (PMID 26942885, 2016). "We have found that rs763361 in CD226 is associated with type 1 diabetes risk, greater frequency of GAD autoantibody, and lower C-peptide levels in a Brazilian cohort, reflecting a more aggressive pattern of autoimmune disease." (PMID 24891767, 2014). "Furthermore, CD226 has also been found to play roles in other autoimmune diseases." (PMID 40723878, 2025). "Interestingly, genome-wide association studies have linked a polymorphism in CD226 to multiple human autoimmune diseases including MS and T1D, suggesting that the TIGIT:CD226 pathway may also play a role in human autoimmunity." (PMID 31974523, 2020). "Despite evidence of the genetic associations of CD226 with autoimmune diseases and dysfunctional Tregs, as well as studies noting that CD226+TIGIT− Tregs are associated with reduced suppressive capacity, the exact molecular mechanism and function role of CD226 in Tregs is poorly understood." (PMID 32983109, 2020).
autoimmune disease (continued). "The findings that CD226 ligation could promote IL-10 cytokine secretion led us to further investigate whether CD226 is involved in the development of autoimmune diseases such as EAE, a murine model for human multiple sclerosis, which has been proved to be regulated by Th1/Th17 as well as Tregs." (PMID 26942885, 2016). "The PVR/TIGIT/CD226/CD96 signalling axis represents a promising therapeutic target for both cancer immunotherapy and the treatment of autoimmune diseases." (PMID 36944702, 2023). "As the CD226–TIGIT axis is centrally involved in the Th1/Th17 balance in cancer and autoimmunity, possible side effects of TIGIT blockade include exacerbation of autoimmune diseases similar to combined PD-1/CTLA-4 blockade." (PMID 35410311, 2022). "However, the role of the TIGIT/CD226 axis in autoimmune diseases remains unclear." (PMID 33413573, 2021). "Previous genome-wide association studies also revealed an important link between the CD226/TIGIT immune checkpoint and autoimmune diseases; however, its relationship with the pathogenesis of PBC has not been illustrated." (PMID 32793241, 2020). "The autoimmune disease studies published to date have mainly focused on one single receptor, i.e., either TIGIT or CD226." (PMID 32793241, 2020). "CD226, also known as DNAX accessory molecule-1 (DNAM-1) or platelet and T cell activation antigen 1 (PTA1), is involved in various pathological processes including autoimmune diseases, tumor, transplantation rejection and virus infection diseases." (PMID 26942885, 2016). "Therefore, it remains to determine whether CD226 Gly307Ser (rs763361) contributes specifically to the expression of the arthritic phenotype in RA or does it just reflect a common genetic background between autoimmune diseases." (PMID 25685070, 2015). "CD226 and TIGIT are expressed at varying levels depending on the T cell subsets and activation states, and imbalance of the CD226/TIGIT signal is involved in the pathogenesis of cancer, autoimmune diseases, and inflammatory responses." (PMID 39349422, 2024). "Therapeutic approaches targeting CD226 in autoimmune diseases exclusively affect proinflammatory Th1 and Th17 cells because naïve T cells do not express CD226." (PMID 34298735, 2021). "Thus, we provide further mechanisms by which CD226 molecules are involved in Treg functions in EAE and evidence for the potential therapeutic effect of targeting CD226 in autoimmune diseases." (PMID 32983109, 2020). "Thus, the results of this study identify additional mechanisms by which CD226 regulates Treg functions in EAE and supports the potential therapeutic effects of anti-CD226 molecules on autoimmune diseases." (PMID 32983109, 2020). "Dermatomyositis (DM) is an autoimmune disease, in which T cell dysregulation plays a pivotal role, and importantly, it is a common immune-related adverse event in response to treatment of cancers with immune checkpoint inhibitors, but no studies have implicated the TIGIT/CD226 axis in DM." (PMID 33413573, 2021).
ovarian carcinoma (25 papers, 2010 to 2025). A malignant neoplasm originating from the surface ovarian epithelium. "Collectively, these data indicate that in PB- and MA-derived macrophages from high-grade ovarian cancer patients the increased frequency of TIGIT, CD226, TIM-3, and LAG-3 positive cells is associated with an M2 phenotype." (PMID 37876933, 2023). "A TIGIT/CD226 dysbalance with high TIGIT and low CD226 expression on intra-tumoral NK cells been shown in multiple human tumors, e.g. colorectal cancer (CRC), ovarian cancer and HCC, and compromises intra-tumoral NK cell functions." (PMID 34367161, 2021).
myeloma (23 papers, 2012 to 2025). "Likewise, the loss of CD8+CD226+ T cells in multiple myeloma has been shown to be associated with suboptimal response to cyclophosphamide (CTX) and bortezomib." (PMID 39777847, 2025). "In multiple myeloma, CD226 limits spontaneous multiple myeloma development and enhances the efficacy of treatment with cyclophosphamide and bortezomib." (PMID 40723878, 2025). "As a co-inhibitory receptor that can be expressed on the surface of effector T and NK cells, it binds to the ligands CD155 and CD112 on the surface of myeloma cells (or antigen-presenting cells) by competing with its co-stimulatory counterpart CD226 (DNAM-1)." (PMID 38017516, 2023). "In particular, CD226 has been shown to be induced by bortezomib on both NK cells and γδ T cells resulting in an improved cytotoxic activity against multiple myeloma cells." (PMID 36428727, 2022). "The first investigation along this line revealed the importance of CD226 for immune surveillance of myeloma." (PMID 34149703, 2021). "Additionally, we found that CD226+ T cells were enriched with NK‐T‐like cells, with prominent cytotoxic capabilities, and have been linked to a better clinical outcome in CLL, multiple myeloma, and colorectal cancer." (PMID 39777847, 2025). "Lack of CD226 reduced the anti-myeloma response of NK and CD8 T cells, resulting in quicker tumor progression and decreased overall survival of Vκ*MYC mice." (PMID 34149703, 2021). "Chemotherapeutic drugs, including doxorubicin, melphalan and bortezomib, upregulate both the DNAX accessory molecule-1 (DNAM-1; CD226) ligand PVR (poliovirus receptor; CD155) and NKG2D ligands (MICA and MICB) on multiple myeloma cells presenting a senescent phenotype." (PMID 32164335, 2020).
breast carcinoma (20 papers, 2007 to 2025). "Next, we employed the data from GSE20685 to better confirm the relationships between gene expression and OS in different cancer stages, and found CD226 was firmly associated with good prognosis in stage II breast cancer patients." (PMID 33549054, 2021). "To further explore the identified CD226, KLRD1, and KLRC4-KLRK1 genes with prognostic value, we analyzed the expression of these genes and their association with OS in different breast cancer stages or subtypes." (PMID 33549054, 2021). "The top GO terms of the upregulated DEGs from the high vs low immune score groups exhibited better prognosis in breast cancer; 15 of them were related to good prognosis in breast cancer, especially CD226 and KLRC4-KLRK1." (PMID 33549054, 2021). "Gene expression analysis also suggested decreased expression of adhesion molecules such as cadherin-related family member 3, CD226, Claudin 7 and Ocludin, upon breast cancer cells exposure to LDL." (PMID 24428917, 2014). "Their findings unveiled a gradual reduction in the expression of NK cell activating receptors, such as NKp30, NKG2D, DNAM-1, CD16, CD226, and 2B4, as breast cancer progressed." (PMID 38533507, 2024). "High CD226 and KLRC4-KLRK1 expression levels were identified, and their correlation with better OS in specific stages or subtypes of breast cancer was validated." (PMID 33549054, 2021). "CD226, KLRC4-KLRK1 and subsequent new targets seem to be promising avenues for promoting antitumor targeted therapy in breast cancer." (PMID 33549054, 2021). "High CD226 expression was related to better prognosis in stage II and stage III breast cancer, as well as in luminal B breast cancer." (PMID 33549054, 2021). "CD226, KLRC4-KLRK1 and other new targets seem to be promising avenues for promoting antitumor targeted immunotherapy in breast cancer." (PMID 33549054, 2021). "High CD226 and KLRC4-KLRK1 expression levels were identified and validated to correlate with better overall survival in specific stages or subtypes of breast cancer." (PMID 33549054, 2021). "Thus, our validation datasets partly proved that high CD226 and KLRC4-KLRK1 expression levels would predict satisfied overall survival of breast cancer, especially in specific stages." (PMID 33549054, 2021). "In other stages or subtypes of breast cancer, CD226 and KLRC4-KLRK1 expression was not significantly related to OS." (PMID 33549054, 2021). "However, the data from GSE20685 showed the reversed results; instead of CD226, KLRC4-KLRK1 was related to good prognosis in breast cancer." (PMID 33549054, 2021). "Additionally, CD226 and CD96 upregulation was observed on NK cells of relapse free breast cancer patients and CD226 was found to be decreased on anergic NK cells associated with lung cancer." (PMID 30908480, 2019).
type 1 diabetes (18 papers, 2010 to 2025). "Among the 285 disease-associated genes, CD69, PLGRKT, and CD226 have also been implicated in recent genome-wide association studies (GWAS) of type 1 diabetes, highlighting the potential significance of these genes in type 1 diabetes." (PMID 41462339, 2025). "For instance, the CD226 Gly307Ser mutation on 18q22 has been implicated in predisposing individuals to type 1 diabetes, multiple sclerosis, and possibly autoimmune thyroid disease." (PMID 39639321, 2024). "Complementary to our identification of NK cell expression CD226 as a risk factor for type-1 diabetes and multiple sclerosis, we identify NK cell expression of CD226 as a determinant of both systemic lupus erythematosus and primary biliary cirrhosis." (PMID 35835762, 2022). "Previous studies have shown that Cd226 gene polymorphism is associated with the incidence of type 1 diabetes." (PMID 34823548, 2021). "We found that rs763361 in CD226 is associated with type 1 diabetes risk, mainly in females, and with greater frequency of GAD autoantibody and lower C-peptide levels, probably reflecting a more aggressive pattern of autoimmune aggression." (PMID 24891767, 2014). "In this report we show that rs763361 in exon 7 of CD226 is associated with type 1 diabetes risk in a Brazilian Cohort (P = 0.0044)." (PMID 24891767, 2014). "Of note, within the CD226 gene (18q22) the rs763361 SNP was found to be associated with type 1 diabetes." (PMID 20089178, 2010). "The current study supports the rs6679677 (PHTF1-PTPN22), rs17696736 (C12orf30) and rs763361 (CD226) SNPs as susceptibility factors for type 1 diabetes outside the major histocompatibility region (MHC) region." (PMID 20089178, 2010). "The nonsynonymous single nucleotide polymorphism (SNP) rs763361/Gly307Ser in exon 7 of CD226 leads to the substitution of serine for glycine in the amino acid sequence of CD226 and has been associated with increased risk for type 1 diabetes, MS, rheumatoid arthritis and autoimmune thyroid disease." (PMID 21457546, 2011). "Furthermore, we confirmed that the rs763361 SNP in the CD226 gene was associated with susceptibility to type 1 diabetes." (PMID 20089178, 2010). "Therefore, the aim of this study was to investigate the contribution of CD226 sequence variants to susceptibility to type 1 diabetes in our population and to correlate risk variants with clinical data, autoantibody status, C peptide levels, and HLA (DR) alleles." (PMID 24891767, 2014). "CD226-deficient NOD mice have reduced incidence of diabetes, and polymorphisms in the CD226 gene are associated with type 1 diabetes in humans." (PMID 38533515, 2024). "Further supporting the role of CD226 in promoting CD8+ T cell pathogenicity in type 1 diabetes, CD226 KO mice showed evidence of reduced TCR avidity of IGRP-reactive CD8+ T cells within the pancreas." (PMID 33013915, 2020). "We report that CD226 KO attenuates type 1 diabetes via altered thymocyte development in combination with impaired peripheral CD8+ T cell activation and IGRP-specific TCR avidity." (PMID 33013915, 2020). "CD226 rs763361 variant increases susceptibility to type 1 diabetes (T1D) in Caucasians." (PMID 24891767, 2014). "We show novel evidence that CD226 KO provided protection from type 1 diabetes in NOD mice." (PMID 33013915, 2020). "We hypothesized the genetic deletion of Cd226 would attenuate disease development, whereas disruption of Tigit would promote type 1 diabetes." (PMID 33013915, 2020). "We sought to determine whether the protection from type 1 diabetes seen in the global CD226 KO mouse could be attributed to the altered function of CD4+ or CD8+ T cells." (PMID 33013915, 2020). "Additionally, treatment of NOD mice with CD226 blocking antibody should be utilized to uncouple the effects of CD226 deletion on thymic selection versus peripheral tolerance, while validating our observation of CD226 disruption preventing type 1 diabetes onset." (PMID 33013915, 2020).
type 1 diabetes (continued). "Similar proportions of type 1 diabetes seen in CD226 WT and HET mice suggested that a single copy of Cd226 was sufficient for maximal type 1 diabetes induction." (PMID 33013915, 2020). "To understand the impact of CD226 KO on CD8+ T cell autoreactivity, we characterized CD8+ T cells recognizing an immunodominant type 1 diabetes epitope, islet-specific glucose-6-phosphatase catalytic subunit-related protein (IGRP206–214)." (PMID 33013915, 2020). "Therefore, we sought to understand how CD226 and TIGIT impact central and peripheral tolerance mechanisms in the context of type 1 diabetes." (PMID 33013915, 2020). "Female and male CD226 HET mice showed similar kinetics of early disease development as compared to WT mice, suggesting that a single copy of the gene was sufficient to promote type 1 diabetes." (PMID 33013915, 2020). "This suggests that the decreased lacrimal disease in the CD226 KO mice may be attributed to CD8+ T cell alterations, in agreement with our findings regarding CD226 impacting CD8+ T cell numbers, memory formation, and TCR avidity in the context of type 1 diabetes." (PMID 33013915, 2020). "While the roles of CD226 and TIGIT in type 1 diabetes pathogenesis remain unclear, blockade of CD226 has been shown to protect from experimental autoimmune encephalitis (EAE), another autoimmune mouse model in which disease pathogenesis is thought to be primarily T cell-mediated." (PMID 33013915, 2020). "It is likely that CD226 drives pathogenicity in both cell types, and further interrogation of CD4+ T cell phenotype in the CD226 KO mouse may uncover mechanisms by which CD226 expression on CD4+ T cells contributes to type 1 diabetes." (PMID 33013915, 2020). "We hypothesized that genetic deletion of Cd226 in the non-obese diabetic (NOD) mouse would impact type 1 diabetes incidence by altering T cell activation." (PMID 33013915, 2020). "While we observed that expression of CD226 on both CD4+ and CD8+ T cells increased the frequency of type 1 diabetes incidence, we did not detect any changes in the thymic development or peripheral activation of CD4+ T cells in the absence of CD226." (PMID 33013915, 2020). "Notably, the Idd21.1 risk locus of the non-obese diabetic (NOD) mouse model of type 1 diabetes contains the Cd226 gene and is orthologous to the 18q22.2 region containing the human CD226 gene, thereby making the NOD mouse a superb in vivo model of CD226 activity in the context of autoimmunity." (PMID 33013915, 2020).